EGR1 (early growth response 1)
Diseases named in the same sentence as EGR1 in open-access papers (continued):
Sharing a sentence is not in itself a finding about the gene and the disease.
breast carcinoma (continued). "In ER+ breast cancer cells, EGR1 is induced by estrogen treatment following raf-1 kinase activation and is inhibited with acquired resistance to ICI." (PMID 29228577, 2017). "Decreased levels of EGR1 in ER+ breast cancer cells and human tumors correlated with decreased sensitivity to antiestrogens." (PMID 29228577, 2017). "In this study, we investigated the role of EGR1 in endocrine resistance to validate an integrated model consisting of differentially expressed genes and metabolites in endocrine resistant breast cancer cells." (PMID 29228577, 2017). "Overall, our gene-metabolite integrated model suggests a novel role for EGR1 in regulating cellular metabolism in endocrine resistant breast cancer." (PMID 29228577, 2017). "On the other hand, the expression of EGR1 is frequently low in lung cancers, breast cancers and ovarian cancers, which resulted in tumor suppression." (PMID 29246166, 2017). "We tested our model by further elucidating the role of EGR1 in endocrine sensitive and resistant breast cancer cells." (PMID 29228577, 2017). "EGR1 has been described as a tumor suppressor gene in most human cancers, including fibrosarcoma, glioblastoma, and breast cancer." (PMID 29340052, 2017). "In an ER+, carcinogen-induced (7,12-dimethylbenz(a) anthracene; DMBA), rat mammary tumor model, EGR1 levels in tumors were reduced relative to normal mammary tissues but then increased with TAM treatment." (PMID 29228577, 2017). "Silencing of EGR-1 with syntactic catalytic DNA has been reported to inhibit human breast carcinoma proliferation and migration, while on the other hand downregulation of gelsolin (indicator of breast cancer) has been correlated with suppression of EGR-1." (PMID 28758926, 2017). "For example, EGR1 is induced by E2 in MCF-7 cells, suggesting that EGR1 is a mediator of the established E2 mitogenic effects in this human breast cancer cell line." (PMID 27035670, 2016). "We tested this on the breast cancer cell line MCF7 for which sequence data from both input material as well as multiple ChIPseq experiments for a number of DNA-associated proteins (ER, EGR1, GATA3, CTCF, MAX, and EP300) are available." (PMID 25887352, 2015). "A miR-191 dependent repression of protein level was shown for NDST1 in MGC803s, CDK6 and SATB1 in human epidermal keratinocytes, and CCND2, CSDA, and EGR1 in the human breast cancer cell line MDA-MB-231." (PMID 25992613, 2015). "The pathway responsible for the paclitaxel-mediated MDR1 overexpression in MCF-7 breast cancer cells is via early growth response gene-1 (egr-1)." (PMID 26049416, 2015). "Suppressed EGR1 levels have previously been reported in breast carcinoma, glioblastoma and lung cancer, where it was predictive of poor outcome." (PMID 25885340, 2015). "Recently, the role of EGR1 has been highlighted in breast cancer cell model and HDAC inhibitors can induce this transcription factor." (PMID 26343742, 2015). "One study showed that several PPARγ ligands including TZD induced the expression of Egr-1 through PPARγ-independent pathway in breast cancer cells." (PMID 24925061, 2014). "It represses the expression of EGR1 and functions as an oncogene in breast cancer, but it also targets the Ezrin gene and inhibits cell migration in T47D cells." (PMID 25394902, 2014). "EGR1 inhibits angiogenesis, suppresses breast cancer and other tumor cells' growth in vitro and in vivo and was significantly reduced in some cancers including breast cancer." (PMID 24980816, 2014). "In summary, the transcription factor EGR1 is a key regulator in the transcriptional control of miR-20b, which is aberrantly expressed in breast cancer tissues and cell lines." (PMID 23945289, 2013). "Our findings demonstrate that EGR1 is associated with miR-20b expression in IR-exposed HMEC cells, breast cancer cell lines and tissues examined, and that EGR1 interacts with the miR-20b promoter and functionally regulates miR-20b transcription." (PMID 23945289, 2013).
breast carcinoma (continued). "We focus our attention on the early growth response 1 (EGR1), a member of the early growth response (EGR) transcription factor family that has been implicated in breast cancer progression and antiestrogen resistance." (PMID 23505378, 2013). "We demonstrated that miR-191 protects ERα positive breast cancer cells from hormone starvation-induced apoptosis through the suppression of tumor-suppressor EGR1." (PMID 23505378, 2013). "Taken together, these results highlight the proliferative effects of E2-induced miR-191/425 cluster in ERα positive breast cancer cells that are in part related to the miR-191 repression of the tumor-suppressor gene EGR1." (PMID 23505378, 2013). "We also show that miR-20b is upregulated in HCC1806 breast cancer cells, and this upregulation correlates with EGR1 expression." (PMID 23945289, 2013). "qRT-PCR showed an aberrant expression of miR-20b in the breast cancer cell lines examined, which correlated with EGR1 expression, with the exception of MCF7." (PMID 23945289, 2013). "Our deduction was confirmed by experiments performed on breast cancer cell lines, in which miR-20b expression was positively correlated with EGR1 expression in the cell lines examined, except for MCF7." (PMID 23945289, 2013). "miR-20b was upregulated by IR and its upregulation correlated with EGR1 expression in the breast cancer cell line HCC1806." (PMID 23945289, 2013). "In a previous study, EGR-1 expression was revealed to be profoundly reduced in human breast cancer tissues and in various cell lines." (PMID 23251236, 2013). "Our data indicated that EGR1 expression was significantly correlated with miR-20b expression in normal, benign, and breast cancer tissues (Pearson Correlation r=0.99)." (PMID 23945289, 2013). "In most human tumors, such as breast cancer, fibrosarcoma, and glioblastoma, EGR1 is described to be a tumor suppressor gene." (PMID 23505378, 2013). "EGR1 is a transcription factor that acts as a tumor suppressor in breast cancer cells, whereas IGFBP1 regulates cell proliferation by binding to and inhibiting IGF1 effects." (PMID 22848683, 2012). "Other researchers have shown that reducing Egr-1 expression in human breast cancer cells can dampen their growth and invasiveness." (PMID 19200397, 2009). "A closer look at the eight Ox-E/ER genes linked to these growth factors revealed that most (EGR1, PHLDA1, IGFBP5, TAGLN, DAB2, and FHL2) have been associated with breast cancer." (PMID 18631401, 2008). "The pattern of retinoid responsiveness for six of 13 target genes (RARβ2, CYP26A1, CRBP1, RGS16, DUSP6, EGR1) correlated with phenotypic retinoid sensitivity, across a panel of retinoid-sensitive or -resistant lung and breast cancer cell lines." (PMID 16012519, 2005). "In other findings, knockdown of EGR1 using EGR1 siRNA enhanced the growth and chemosensitivity of breast cancer cell lines to capsaicin.It is now reported that EGR1 can promote pancreatic cancer migration and invasion by controlling the expression of SNAI2 and modulating the EMT pathway." (PMID 38408959, 2024). "EGR1 has also been shown to play a cancer-suppressing role in breast cancer." (PMID 39044249, 2024). "The miRNA-triggered entropy-driven reconfiguration of the spatiallylocalized circuit leads to the programmable, cooperative bis-gene-silencingof HIF-1α and EGR-1 mRNAs, resulting in the effective and selectiveapoptosis of breast cancer cells and effective inhibition of tumorsin tumor bearing mice." (PMID 39012486, 2024). "We identified the biological effect and molecular mechanisms of EGR1 in breast cancer (BC)." (PMID 39006084, 2024). "The overexpression of EGR1 has been revealed to act as an inhibitor in breast cancer." (PMID 38248651, 2023). "When the EGR1 signal was dampened in breast cancer by EZH2, cell growth, migration, and invasion, and tumorigenesis of breast cancer cells could be recovered or strengthened." (PMID 37188478, 2023).
breast carcinoma (continued). "Conversely, some forceful outcomes define EGR1 as a tumor suppressor in breast cancer." (PMID 37188478, 2023). "However, patients with breast cancer exhibiting upregulated expression levels of FOS, FOSB, EGR1, and EGR3 were associated with improved prognosis." (PMID 37233869, 2023). "Moreover, we found that the PD-L1-deficient breast cancer cells (MDA-MB-231 and MDA-MB-436) exhibited decreased levels of EGR1 and VEGFA." (PMID 36977660, 2023). "Besides, miR-20b expression has been correlated with expression levels of EGR1 in breast cancer tissues." (PMID 36582800, 2022). "In addition to this, it has been shown that attenuating the nuclear fraction of EGR1 apparently inhibits the survival of breast cancer cells by inhibiting MAPK phosphorylation." (PMID 35886025, 2022). "Several previous studies showed that EGR1 exhibits prominent tumor suppressor function in glioma, non-small-cell lung cancer, colon cancer, papillary thyroid carcinoma, and breast cancer." (PMID 35812443, 2022). "Targeting the EGR1 with DNAzymes significantly inhibited the growth of breast cancer solid tumors." (PMID 34889888, 2021). "Moreover, the IHC assay showed that the EGR1 protein expression in breast cancer tissue was clearly decreased compared with that in normal breast tissue." (PMID 33472669, 2021). "Collectively, these data indicate that CTCF and EGR1 act as transcription factors to drive Nm23-H1 expression in less metastatic breast cancer cells, whereas their lower expression in aggressive breast cancers may contribute to reduced levels of Nm23-H1." (PMID 33436746, 2021). "This indicates that the EGR1 gene should play an essential role in breast cancer progression." (PMID 34889888, 2021). "miR-183, as an oncogene in breast cancer, represses the expression of EGR1." (PMID 32040529, 2020). "In accordance with this context, we illustrated that EGR1 may be a BD's target for breast cancer treatment." (PMID 32714860, 2020). "Furthermore, inhibition of EGR-1 by DNAzyme inhibits fibroblast growth factor-dependent angiogenesis in breast cancer." (PMID 33053908, 2020). "Our further study discovered that SUV420H2-targeting miR-29a could promote EMT of breast cancer cells via down-regulating H4K20me3, which attenuated the repression of EGR1 and CTGF." (PMID 30792382, 2019). "In breast cancer, miR-425 promoted cell proliferation through suppressing EGR1." (PMID 30285885, 2018). "Ionizing radiation (IR) elicits an increase in miR20b and Egr-1 expression in breast cancer." (PMID 30400241, 2018). "Furthermore, breast cancer cells expressing constructs targeting EGR1 and NDRG1 displayed an increase in breast cancer cell migration." (PMID 30337371, 2018). "Results from the siRNA and cDNA experiments suggest that disrupted EGR1 expression may have a subtle impact on the metabolic profile of LCC9 breast cancer cells." (PMID 29228577, 2017). "Targeting EGR1 with TOLE may be an effective therapeutic strategy in some endocrine resistant breast cancers." (PMID 29228577, 2017). "In normal murine fibroblasts, normal hippocampal neurons, melanoma cells, a variety of human tumor cell lines, gliobastoma, non-small cell lung cancer, breast carcinoma, skin cancer as well as head and neck cancer, EGR1 is either pro-apoptotic or suppresses growth." (PMID 28081176, 2017). "EGR1 mediated signaling is important for the normal development of female reproductive organs but its precise role in breast cancer remains unclear." (PMID 29228577, 2017). "In agreement with the role of EGR1 in non-small cell lung cancers, breast cancer, glioblastomas, and acute myelogenous leukemia, our data support the hypothesis that EGR1 acts as a tumor suppressor in HCC." (PMID 27244890, 2016). "A decrease in EGR1 expression may play an important role in the development of breast cancer and serve as biomarker." (PMID 24980816, 2014). "It must be noted, however, that the role of EGR-1 expression in breast cancer is controversial." (PMID 23251236, 2013).
breast carcinoma (continued). "Furthermore, both EGR1 and miR-20b were overexpressed in 50% metastatic breast cancer tissues compared with normal tissues and were correlated with each other remarkably well." (PMID 23945289, 2013). "Moreover, immunohistochemical and FISH analyses showed that the miR-20b expression correlated significantly with EGR1 levels in breast cancer tissues." (PMID 23945289, 2013). "To explore our hypothesis, we determined the expression of EGR1 and miR-20b, as well as the contribution of EGR1 to miR-20b transcription in breast cancer cells." (PMID 23945289, 2013). "EGR1 was found to be up regulated in a variety of cancer including breast cancer." (PMID 24278004, 2013). "Furthermore, DNAzymes targeting EGR1 inhibit breast cancer cell proliferation, migration and tumor growth in nude mice although the underlying mechanisms are still unclear." (PMID 23945289, 2013). "Finally, immunohistochemical and FISH analyses indicate that miR-20b is elevated in 30% of breast cancer and 50% of metastatic breast cancer specimens examined, and this upregulation correlates significantly with EGR1 levels." (PMID 23945289, 2013). "More important, EGR1 was overexpressed in 50% of the metastatic breast cancer tissues examined." (PMID 23945289, 2013). "Furthermore, senescence suppression by TBX2 in human cells depends on the physical interaction of TBX2 with tumor suppressive TFs, for example EGR1 in breast cancer cells, and PML in fibroblasts." (PMID 22844464, 2012). "Based on published associations to breast cancer-specific tumor biology, a steroid response module (SR), a basal breast cancer module (basal), and a module containing genes (for example, FOS and EGR1) related to early response to growth factor or serum stimulation (early response) were identified." (PMID 22839103, 2012). "R educing nuclear EGR1 levels could significantly inhibit breast cancer cell growth." (PMID 40519297, 2025). "Collectively, these results indicate that breast cancer cells may utilize CTCF and EGR1 to drive Nm23-H1 expression and suppress the invasive phenotype, whereas the downregulation of these proteins in aggressive breast cancers potentially contribute to cancer metastasis." (PMID 33436746, 2021). "EGR1 may be a relevant therapeutic target in treating this highly aggressive breast cancer subtype." (PMID 32444778, 2020). "This gives rise to the possibility that EGR-1-dependent signaling loop and the TNFα-EGR-1–CYP19–estrogen-EGR-1 axis could result in persistent activation of estrogen production, thereby facilitating the development of ER-positive breast cancer in the tumor microenvironment." (PMID 33053908, 2020). "In conclusion, our results suggested that PN-1, which is up-regulated in breast cancer cells and BCSCs through EGF/PKC/MAPK/EGR1 signaling, is related to poor prognosis and could serve as a positive-feedback regulator in breast cancer cells metastasis and stemness." (PMID 31501409, 2019). "Additionally, we found genes highly expressed in breast cancer stroma in the Human Protein Atlas (EGR1, OSBPL8, FAM171A2, FGD6, and CEP131), or likely expressed in fibroblasts (MMP13), that are reported to play a role in breast cancer progression among the most important ones." (PMID 31505876, 2019). "Hence, the EGF/EGFR/PKC/MEK/ERK/EGR1/PN1/HtrA1 signaling axis might be a potential therapeutic target for breast cancer treatment." (PMID 31501409, 2019). "Furthermore, EGR1 levels in human breast tumors may be useful as a favorable prognosis marker in ER+ breast cancer." (PMID 29228577, 2017). "MIDN interacted with NR4A1, EGR1, and PSMC1, and it was especially co-expressed in liver cancer, pancreatic cancer, urothelial cancer, breast cancer and melanoma." (PMID 40002690, 2025).
breast carcinoma (continued). "For example, TBX2 interacts with and requires early growth response 1 (EGR1) to inhibit the tumour suppressor genes N-myc downstream-regulated gene 1 (NDRG1) and cysteine protease inhibitor cystatin 6 (CST6) to promote breast cancer cell proliferation." (PMID 39912718, 2025). "GPER is crucial for BPA-mediated ERK1/2 activation and induces expression of c-Fos, EGR-1, and CTGF, promoting proliferation in certain breast cancer cells." (PMID 39170668, 2024). "Approximately 30% more cells of the macrophage subtypes positive for LAM2_APOE, LAM1_FABP5 and EGR1, respectively, expressed CLEC10A in TNBC in comparison with ER+ / HER2+ breast cancer (Chi-squared p < 0.001)." (PMID 38206856, 2024). "The environmental pollutant BPA is linked to GPER action in testicular seminoma cells and upregulates GPER target genes: c-fos, early growth response-1 protein (EGR-1), and connective tissue growth factor (CTGF) in breast cancer cells and stromal fibroblasts." (PMID 37887304, 2023). "The FOS, FOSB, EGR1, and EGR3 expression levels in healthy breast tissues were higher than in breast cancer tissues." (PMID 37233869, 2023). "In breast cancer, eight winning TFs (ZBTB16, KLF2, KLF4, NR2F1, EGR1, FOSB, EPAS1, and GPRASP1) can form a coregulatory network, and three other winning TFs (MYBL2, FOXM1, and TAL1) can form another coregulatory network." (PMID 36101460, 2022). "FOS, also known as AP-1 subunit, is a major proto-oncogene, EGR1 has been reported to activate the transcription of miR-20b and thereby inhibit the expression of PTEN (a tumor suppressor gene) in breast cancer." (PMID 34151031, 2021). "In breast cancer, S100A4 drives the nuclear localization of EGR1 by promoting the binding of EGR1 to importin 7, and EGR1 next enhances tumor invasion and metastasis by downregulating β-catenin through the PTEN–AKT–GSK3β signal transduction." (PMID 33842351, 2021). "Meanwhile, the rs2236007 site can decrease the expression level of a breast cancer-related gene, PAX9 (HGNC:8623), via altering the binding of the repressive transcription factor, EGR1." (PMID 34889888, 2021). "In the 0.5 and 1.5 μM BD-treated MCF-7 breast cancer cells, the expression levels of ZFP36 and EGR1 were markedly increased compared with DMSO-treated." (PMID 32714860, 2020). "As indicated by the results, the transcriptional levels of EGR1, EGR2, and EGR3 were significantly reduced in patients with BRCA (p < 0.05), whereas the expression level of EGR4 was very low in both breast cancer and normal breast tissues." (PMID 33614706, 2020). "The EGFR/ERK1/2 signaling cascade upregulates the expression of Egr-1 that in turn participates in the transcription of CTGF and cyclin D1, two genes that regulate breast cancer growth." (PMID 33117280, 2020). "By suppressing the expression of SUV420H2, which leads to the loss of H4K20me3, miR-29a attenuates the repression of CTGF and EGR1 by H4K20 trimethylation and promotes the EMT progress and metastasis of breast cancer cells." (PMID 30792382, 2019). "EGR1 expression mediates an EGF-ERK signaling cascade was reported in prostate cancer cells and breast cancer cells, which contributes to the migration of cancer cells." (PMID 31501409, 2019). "SS-inducible genes such as the Egr1 drive expression of Ap1, a transcription factor composed of protein dimers of c-JUN and c-FOS, which contributes to EPCAM-dependent breast cancer invasion." (PMID 30651129, 2019). "In conclusion, we identified a novel signaling pathway of EGF-mediated up-regulation of PN-1 in breast cancer cells, which requires cascade activation of EGFR/PKCδ/MEK/ERK/EGR1, which was crucial for breast tumor metastasis and BCSC stemness." (PMID 31501409, 2019). "In breast cancer, it has been shown that the T-box transcription factor family member, TBX2, interacts with EGR1 and this interaction abrogates EGR1 function as a tumor suppressor and downregulates the transcription of the EGR1 gene-dependent program." (PMID 29719592, 2018).